PHF21B (PHD finger protein 21B)
Synonyms: BHC80L; FLJ34161; PHF4
Tractability: No criterion of Open Targets' tractability assessment is met for any kind of drug.
Gene: Protein-coding gene on chromosome 22 (44,881,162 to 45,010,022, reverse strand). Ensembl gene ENSG00000056487.
Subcellular location (Human Protein Atlas): Nucleoli fibrillar center; Nucleoplasm; Cytosol
Genetic constraint (gnomAD): Loss-of-function variants: 22 observed, 46.47 expected, observed/expected ratio (o/e) 0.47, 90% interval 0.34 to 0.68. The synonymous counts are far from expectation, so gnomAD's model fits this gene poorly and the ratio says little. Missense variants: 661 observed, 600.15 expected, observed/expected ratio (o/e) 1.1, 90% interval 1.03 to 1.17. Synonymous variants: 328 observed, 263.13 expected, observed/expected ratio (o/e) 1.25, 90% interval 1.14 to 1.37.
Homologues: Orthologues: macaque PHF21B (97% identical), chimpanzee PHF21B (92% identical), dog PHF21B (86% identical), pig PHF21B (86% identical), mouse Phf21b (81% identical), rat Phf21b (79% identical), guinea pig PHF21B (79% identical), tropical clawed frog phf21b (62% identical), zebrafish phf21b (44% identical). Paralogues in human: PHF21A (36% identical), AIRE (15% identical), ZMYND8 (14% identical), PHF12 (11% identical), ZMYND11 (7% identical).
Diseases named in the same sentence as PHF21B in open-access papers:
PHF21B is named in the same sentence as 11 diseases in open-access papers, as found by Europe PMC text mining. Sharing a sentence is not in itself a finding about the gene and the disease. The quoted sentences say what the papers report.
head and neck squamous cell carcinoma (2 papers, 2017 to 2021). A squamous cell carcinoma that arises from any of the following anatomic sites: lip and oral cavity, nasal cavity, paranasal sinuses, pharynx, larynx, and salivary glands. "However, PHF21B has also been found to act as a tumor suppressor in head and neck squamous cell carcinomas." (PMID 34433810, 2021). "Previous study has reported that PHF21B was downregulated in head and neck squamous cell carcinomas (HNSCC), and reduced MDA-MB231 cells migration and colony formation in vitro." (PMID 28645312, 2017).
prostate carcinoma (2 papers, 2017 to 2021). A carcinoma that arises from epithelial cells of the prostate gland. "Gain-of-function and loss-of-function studies showed that overexpression of PHF21B enhanced, while downregulation suppressed, the cancer stem cell-like phenotype in prostate cancer cells." (PMID 28645312, 2017). "In prostate cancer, PHF21B overexpression has been found to promote CSC-like traits cells by activating the Wnt/β-catenin signaling pathway." (PMID 34433810, 2021). "Our results revealed that PHF21B was markedly upregulated in prostate cancer cell lines and tissues." (PMID 28645312, 2017). "Real-time PCR, immunohistochemistry and western blotting analysis were used to determine PHF21B expression in prostate cancer cell lines and clinical specimens." (PMID 28645312, 2017). "The role of PHF21B in maintaining prostate cancer stem cell-like phenotype was examined by tumor-sphere formation assay and expression levels of stem cell markers." (PMID 28645312, 2017). "In addition, PHF21B, a gene that can promote stem-like characteristics in prostate cancer cell lines contains predicted binding sites for miR-527." (PMID 34433810, 2021). "Overexpression of PHF21B in PCa was confirmed by analyzed prostate cancer GEO dataset GSE21032." (PMID 28645312, 2017). "This study is aimed to study the role of PHF21B in the progression of prostate cancer." (PMID 28645312, 2017). "Our results revealed that PHF21B functions as an oncogene in prostate cancer, and may represent a promising prognostic biomarker and an attractive candidate for target therapy of prostate cancer." (PMID 28645312, 2017). "Notably, Wnt/β-catenin signaling was hyperactivated in prostate cancer cells overexpressing PHF21B, and mediated PHF21B-induced cancer stem cell-like phenotype." (PMID 28645312, 2017). "High PHF21B levels predicted poorer recurrence-free survival in prostate cancer patients." (PMID 28645312, 2017). "PHF21B is newly identified to be involved in the tumor progression; however, its biological role and molecular mechanism in prostate cancer have not been defined." (PMID 28645312, 2017).
autism spectrum disorder (1 paper, 2022). A spectrum of developmental disorders that includes autism, and Asperger syndrome. "Because the human PHF21B gene is located in a chromosomal region linked to autism spectrum disorders, we also tested the sociability of the animals." (PMID 35866480, 2022).
bipolar disorder (1 paper, 2007). A disorder of the brain that causes unusual shifts in mood, energy, activity levels and the ability to carry out day-to-day tasks. "For example, 10 genes among the 16 confirmed genes (Cacng2, Dnajc3, Dusp4, Gpc6, Mbp, Nov, Phf21b, Atxn10, Xbp1, and Zfyve28) have their human orthologs located within a 10 Mb region flanking the linkage markers for bipolar disorder, and thus merit further study." (PMID 18028544, 2007).
breast carcinoma (1 paper, 2017). "PHF21B has been reported to be downregulated in HNSCC, and overexpression of PHF21B reduced MDA-MB231 cells migration and colony formation in vitro, suggesting it might act as a tumor suppressor in HNSCC and breast cancer." (PMID 28645312, 2017).
cognitive deficits (1 paper, 2025). "Additional genes from Regions 2 and 3 (PHF21B, SULT4A1, SCUBE1, and NUP50) we speculate that they may further contribute to cognitive deficits, neurodevelopmental features, and growth abnormalities." (PMID 40429797, 2025).
prostate adenocarcinoma (1 paper, 2017). "We further assessed the correlation between PHF21B expression and the prognosis of the patient by analyzing the TCGA prostate adenocarcinoma (PRAD) dataset." (PMID 28645312, 2017).
tumor (5 papers, 2015 to 2024). "The regulatory target of miR-527 was PHF21B, and tumor tissues from NSCLC patients have considerably higher levels of PHF21B." (PMID 39170516, 2024). "In vitro experiments determined that targeting hsa‐circ0003222 reduced tumour cell proliferation, migration, invasion and stemness‐like properties via downregulation of PHF21B, which increased tumour suppressor miR‐527 levels." (PMID 37735815, 2023). "The levels of hsa_circ_0003222 and PHF21B are meaningfully increased in tumor tissue when miR-527 is inhibited." (PMID 34433810, 2021). "We discovered that PHF21B was the regulatory target of miR-527 and that PHF21B is significantly upregulated in the tumor tissues of patients with NSCLC." (PMID 34433810, 2021). "Sphere-formation assays showed that upregulating PHF21B increased, while downregulating PHF21B decreased, the number and size of tumor spheroids in C4-2B and PC-3 cells." (PMID 28645312, 2017). "Expression of PHF21B correlated significantly with tumor stage (P = 0.011), total PSA level (P = 0.005) and Gleason score (P = 0.001) in PCa." (PMID 28645312, 2017). "Xenograft tumor model showed that silencing PHF21B decreased the ability of tumorigenicity in vivo." (PMID 28645312, 2017). "Therefore, PHF21B seems to function in tumor progression in NSCLC and is regulated by miR-527." (PMID 34433810, 2021). "Therefore, the mechanisms by which β-catenin protein is reduced in PCa tissues with high PHF21B might be attributed to tumor heterogeneity." (PMID 28645312, 2017). "Therefore, the PHF21B may display both tumor suppressive and oncogenic properties depending on the tissue types and cellular conditions." (PMID 28645312, 2017). "Further characterization of PHF21B, revealed that it was significantly upregulated in NSCLC tumor tissues." (PMID 34433810, 2021). "Four genes, PPP1R3C, PHF21B, TPM1 and PPP1R14A, were highly downregulated in the tumor tissues compared with the normal tissues." (PMID 25789025, 2015).
cancer (3 papers, 2017 to 2022). A tumor composed of atypical neoplastic, often pleomorphic cells that invade other tissues. "Previously, we described the PHF21B deletion, loss of function, and changes in DNA methylation in HNC patients with a family history of cancer." (PMID 36552033, 2022). "We located potential binding sites of miR-527 in PHF21B, a gene that has been found to promote cancer stemness." (PMID 34433810, 2021). "A higher expression of PHF21B was found to correlate with DNA methylation, suggesting that epigenetic mechanisms may control its regulation in cancer." (PMID 34433810, 2021).
infection (1 paper, 2017). The state of being infected such as from the introduction of a foreign agent such as serum, vaccine, antigenic substance or organism. "PCa cell lines C4-2B and PC-3 were engineered to overexpress or silence PHF21B via lentivirus infection." (PMID 28645312, 2017).
PHF21B also shares sentences with these, for which no sentence is quoted: psychiatric disorder (1 paper).